TYR (tyrosinase)
Diseases named in the same sentence as TYR in open-access papers (continued):
Sharing a sentence is not in itself a finding about the gene and the disease.
melanoma (continued). "Therefore, we investigated whether PA could inhibit melanin synthesis through inhibition of tyrosinase activity in α-MSH-induced melanoma cells." (PMID 33917915, 2021). "This study investigated ABTS, DPPH and nitric oxide (NO) radical-scavenging activities, and melanin production and TYR inhibitory effects-guided fractionation to identify therapeutic phytochemicals from S. glabrescens that can attenuate oxidation and melanogenesis in murine melanoma B16F10 cells." (PMID 33808322, 2021). "Additionally, small interfering RNA-mediated MITF silencing in melanoma cells significantly reduced melanin content by inhibiting tyrosinase, TRP-1, and MC1R, indicating that inhibition of the transcriptional activation of MITF is also a promising strategy to treat hypermelanogenic disorders." (PMID 34299326, 2021). "Although more extensive and further studies, including human tyrosinase and human melanoma cells studies, are needed for a thorough understanding of the potential inhibitor of PA in melanogenesis, our results confirm that PA could be explored as a possible skin-lightening agent." (PMID 33917915, 2021). "Moreover, the enzyme (acetyl- and butyryl-cholinesterases, α-amylase, α-glucosidase, and tyrosinase) inhibitory and cytotoxicity activities on HepG2: human hepatocellular carcinoma cells, B16 4A5: murine melanoma cells, and S17: murine bone marrow (normal) cells of extracts were evaluated." (PMID 33557215, 2021). "Moreover, in the case of melanoma, the expression of tyrosinase, a key enzyme in melanin synthesis, plays an important role in the progression of the disease as it may decrease cellular response to radiotherapy." (PMID 34577645, 2021). "A recent study in melanoma suggests that this may be possible: RNA-LPX vaccine encoding MAGEA3, NY-ESO-1, tyrosinase and transmembrane phosphatase with tensin homology (TPTE) were tested in checkpoint-inhibitor (CPI)-treated patients with unresectable melanoma." (PMID 32942747, 2020). "Variants in TYR and OCA2 may play a role in amelanotic/hypomelanotic melanoma susceptibility." (PMID 32966289, 2020). "However, in human melanoma cells melatonin may both stimulate tyrosinase activity and pigmentation, as described in SK-MEL-28 and SK-MEL-1 cells, or decrease melanogenesis as reported in MNT-1 melanoma cells." (PMID 32674468, 2020). "Since levodopa is a metabolite in the biosynthesis of dopamine and melanin which involves the enzyme tyrosinase, and increased tyrosinase activity is found in melanoma, it was initially hypothesized that levodopa could enhance and stimulate growth on any residual melanoma tissue." (PMID 32973662, 2020). "Indeed, recent studies reported the safety and efficacy of a DNA vaccine encoding murine tyrosinase for malignant melanoma of the digit of dogs and ONCEPT, a DNA vaccine encoding human tyrosinase for oral malignant melanoma in dogs was approved by the U.S. Department of Agriculture in 2010." (PMID 31164958, 2019). "Therefore, finasteride inhibited tyrosinase in both melanocytes and melanoma cells." (PMID 29397551, 2018). "In addition, inhibition of Calpain by either Calpain inhibitor I (ALLN) or Calpastatin (CS) peptide blocked melanin biosynthesis in mouse B16 melanoma cells, which was correlated with a decrease in the activity of tyrosinase, a key regulatory enzyme in melanogenesis." (PMID 30131853, 2018). "Therefore, it has become a focus to search for new drugs from folk medicine which could inhibit tyrosinase activity and decrease the proliferation of melanoma cell." (PMID 29197358, 2017). "Veterinary xenogeneic vaccinations include a DNA plasmid vaccine encoding human Tyrosinase (TYR) the only veterinary therapeutic tumour vaccine licensed by the United States department of Agriculture (USDA) for the use of oral and digital melanoma, now marketed as OnceptTM." (PMID 28591206, 2017).
melanoma (continued). "Hence, inhibiting tyrosinase activity is a common approach to promote skin whitening, but it could be particularly valuable in the prevention of skin cancers such as melanoma." (PMID 26805794, 2016). "Even though high melanoma risk alleles clearly exist in e.g. CDKN2A, it is speculated if the melanoma risk might be attributable to combinations of low to moderate risk alleles in e.g. MC1R, TYR, and ASIP." (PMID 26938746, 2016). "Treatment with Radix ginseng in the presence of various concentrations of Radix trichosanthis suppressed tyrosinase activity and melanin content but increased cell proliferation slightly in B16 melanoma cells, raising the possibility that this combination may be effective as a skin-lightening agent." (PMID 23431351, 2013). "It was interesting that eleven of the molecules previously implicated in melanoma pathogenesis (described in the introduction) were identified as hubs in the Bayesian gene networks generated from our A375 cell dataset, including: BRAF, CCND1, RB1, PTEN, TYR, CDKN2A, and SOX10." (PMID 22536322, 2012). "Overexpression of EDEM1 in melanoma cells could be an efficient way of accelerating tyrosinase degradation and inducing a more efficient display of peptides at the surface of the melanoma cell leading to an efficient recognition by CTL and the eventual enhanced elimination of melanoma cells." (PMID 22905195, 2012). "Autoantibodies to tyrosinase and to melanin which are found even in healthy people, point that consummation of edible mushrooms that carry the antigen tyrosinase and melanin, could influence the humoral anti-melanoma immune response." (PMID 22834951, 2012). "Interestingly, most of CD271 expressing cells completely or partially lacked the expression of other melanoma tumor antigens, such as tyrosinase and melanoma antigen recognized by T cells (MART1), indicating that CD271+ melanoma cells have a less differentiated phenotype." (PMID 22419851, 2012). "However, the construction of systems based on melanoma-specific promoters, such as promoters of the MIA and TYR genes, could provide a universal, highly efficient, and specific expression of the therapeutic gene in melanoma cells." (PMID 22649681, 2011). "In a genome-wide association (GWA) study of melanoma carried out by the GenoMEL consortium, association was confirmed between disease susceptibility and variants related to melanocortin-1 receptor (MC1R) and tyrosinase (TYR), and a new locus at chromosome 9p21 was identified." (PMID 22216283, 2011). "Tregs redirected with a high-avidity class I-specific TCR were capable of recognizing the melanoma antigen tyrosinase in the context of HLA-A*0201 and could be further enriched during the expansion process by antigen-specific reactivation with peptide loaded artificial antigen presenting cells." (PMID 20668510, 2010). "Moreover, tyrosinase expression appears to be conserved in malignant melanoma cells." (PMID 20498710, 2010). "However, a more likely explanation relates to the findings by the group of Goding, which reported that ectopic expression of Ad E1A resulted in down regulation of Mitf in mouse melan-a melanoma cells, leading to repression of TRP-1 and tyrosinase levels and subsequent loss of pigmentation." (PMID 20670430, 2010). "Therefore, in the present study, to compare the depigmenting effect of catechin derivatives, we investigated the melanogenesis inhibitory mechanisms of the catechins (EGCG, EGC and C) and gallic acid in murine B16 melanoma cells, and we also discuss their effects on the expression of tyrosinase." (PMID 19924076, 2009).
melanoma (continued). "Thus, we comparatively explored the expression not only of Melan-A/MART-1 and gp100 but also of tyrosinase genes, encoding differentiation antigens widely used in active specific immunotherapy in HBL and D10 melanoma cells cultured in either MCTS or conventional 2D conditions." (PMID 17342088, 2007). "In a previous paper, we demonstrated that the majority of untreated stage IV melanoma patients were positive, whereas chemotherapy administration was able to reduce tyrosinase rate, suggesting that tyrosinase may provide a measure of therapy response and be a predictor of disease evolution." (PMID 14562017, 2003). "Detection of tyrosinase mRNA by reverse transcription-polymerase chain reaction (RT-PCR) has been described as an extremely sensitive way of detecting circulating viable melanoma cells in the peripheral venous blood, and this technique may be of value in the early detection of dissemination." (PMID 7599046, 1995). "Recent findings demonstrate that oxyresveratrol effectively decreases tyrosinase function and melanin synthesis in B16F10 melanoma cells." (PMID 41596305, 2026). "In this study, we clarified the importance of anterograde transport of Tyrosinase proteins, which are regulated by BBF2H7 for melanogenesis in the melanoma cell line and primary melanocytes extracted from neonatal mice as the first step." (PMID 41516372, 2026). "In vitro, hAAT upregulated melanocytic differentiation markers (MITF, TYR, PMEL, MART-1) and increased melanin production in murine and human melanoma lines, suggesting enhanced tumor immunogenicity." (PMID 41594664, 2026). "Similar inhibition of melanin production and decreased expression of tyrosinase protein and MITF mRNA and protein were also confirmed in MNT‐1 human melanoma cells." (PMID 40524653, 2025). "The aim of this study was to investigate the anti-melanogenic (including anti-tyrosinase) effects of B. rotunda extract and panduratin A in B16F10 melanoma cells induced by UVA radiation." (PMID 40362555, 2025). "In contrast, amelanotic melanoma cells tend to be less differentiated and are often characterized by reduced expression of pigmentation-related genes (e.g., MITF, TYR) and alternative oncogenic alterations." (PMID 40649764, 2025). "Treatment with 20 and 40 μM fisetin markedly reduced tyrosinase activity in melanoma and α-MSH-stimulated melanoma cells, showing approximately a 50-fold decrease compared with their respective control groups." (PMID 41373883, 2025). "Consistently, the mRNA expression of MITF-regulated melanogenic genes, including tyrosinase, TRP-1, PMEL, and TRP2/DCT, was significantly downregulated in fisetin-treated melanoma cells." (PMID 41373883, 2025). "BNT111, a melanoma mRNA-lipoplex vaccine targeting four TAAs (NY-ESO-1, MAGE-A3, tyrosinase, and TPTE), has already demonstrated safety and immunogenicity in the phase I clinical trial, Lipo-MERIT for advanced melanoma patients." (PMID 41542091, 2025). "Pearl regulated microphthalmia‐associated transcription factors through CREB and affected melasma‐related genes TYR and DCT, which in turn inhibit melanoma cell activity and intracellular tyrosinase activity." (PMID 40369904, 2025). "The application of grass carp fish-scale collagen peptide FTGML significantly inhibited tyrosinase activity and melanin synthesis in B16F10 melanoma cells." (PMID 40001523, 2025). "Other studies have reported that LSE moderately inhibited tyrosinase activity in vitro, and α‐MSH stimulated melanogenesis in murine melanoma cells." (PMID 39305105, 2025). "The tyrosinase inhibitory effect of compound 1, 4-hydroxybenzoic acid (4HB), on pigmented human MM418C1 melanoma cells was also investigated." (PMID 41011583, 2025). "Immunohistochemical studies demonstrated strong positivity for S100, SOX10, and melanoma cocktail (MART-1/Melan-A, HMB-45, and tyrosinase), with negativity for AE1/AE3, CAM5.2, CK7, and HMB-45." (PMID 40984891, 2025).
melanoma (continued). "DCS significantly downregulated the expression of key melanogenic enzymes including tyrosinase, TRP-1, and TRP-2, as well as the master transcription factor MITF, in melanoma cells." (PMID 40869042, 2025). "Findings reveal that CPH3 demonstrates the capability to inhibit melanin production in mouse melanoma cells (B16F10) and to diminish intracellular TYR activity via a paracrine action involving keratinocytes (HaCaT)." (PMID 40001523, 2025). "A preclinical study depicted anticancer activity by suppressing TYR and TRP-1 genes in melanoma cells." (PMID 41346617, 2025). "Western blot analysis showed that EUE treatment under 1.5 mM H2O2 stress increased the expression of MITF, TYR, β-catenin, GSK-3β, p-GSK-3β, and Wnt-5a in B16 melanoma cells." (PMID 41496855, 2025). "To further investigate the role of THC on tyrosinase expression in melanoma, we examined the inhibitory effect of THC on tyrosinase using mushroom tyrosinase." (PMID 41446503, 2025). "In an in vitro study using B16-F10 melanoma cells, α-MSH was found to induce a dose-dependent increase in melanin synthesis, tyrosinase activity, and the expression of key melanogenic proteins, including TRP-1, TRP-2, and MITF." (PMID 40076896, 2025). "Furthermore, total oligomeric flavonoid (TOF) extract from Crataegus azarolus and epicatechin, an active compound of the extract, may influence melanogenesis by inhibiting tyrosinase activity, thus having potential applicability in skin depigmentation and melanoma treatments." (PMID 40508280, 2025). "In the present study, we found that CPEO not only inhibited UVA-induced α-MSH in keratinocytes but also downregulated melanogenesis-related molecules (MITF, tyrosinase, TRP-1, TRP-2) and melanin production in B16BL6 melanoma cells." (PMID 41304724, 2025). "Here, we show that the expression of ERRFI1 was upregulated in melanoma and negatively correlated with the expression of melanocytic differentiation markers, such as MITF and TYR." (PMID 41044875, 2025). "For example, BNT-111, developed by BioNtech Company, is a mRNA-lipoplex vaccine designed for melanoma antigen (MAGE-A3, NY-ESO-1, TPTE, Tyrosinase)." (PMID 40733649, 2025). "SPEF significantly suppressed the elevated levels of MITF, tyrosinase, TRP1, and TRP2 expressions in α-MSH-stimulated melanoma cells." (PMID 40003988, 2025). "Histological markers used to diagnose melanoma are: S100 protein, HMB45, Melan-A, Tyrosinase, MITF and Vimentin." (PMID 39862670, 2025). "Peptide-based vaccines targeting melanoma antigens such as gp100, MART-1, and tyrosinase have shown preliminary immune activation, especially when paired with adjuvants or cytokines that augment antigen presentation." (PMID 40725830, 2025). "The results demonstrated that fisetin treatment led to a marked reduction in MITF and tyrosinase protein levels in both melanoma and α-MSH-stimulated human melanoma cells." (PMID 41373883, 2025). "This situation is thought to be associated with T cells that have the capability to target both melanocytes and melanoma cells expressing tissue antigens, including melanocyte lineage-specific antigen (GP100), tyrosinase, and MART-1." (PMID 39866435, 2025). "Among these, two overlapping targets (TYR and MITF) were considered potential targets for the treatment of melanoma." (PMID 40708947, 2025). "Before validating the TYR degradation, we first evaluated the cytotoxicity of synthesized compounds against human A375 and murine B16F10 melanoma cells, which are both TYR-overexpressing cell lines." (PMID 40651969, 2025). "In melanotic melanoma cells, miR‐211 acts as a direct target of MITF and regulates EDEM1 expression and cell migration, subsequently impairing the degradation of Tyrosinase." (PMID 39823244, 2025). "Other melanoma-specific markers such as human melanoma black 45 (HMB45), tyrosinase, MART-1/Melan-A, melanocyte-inducing transcription factor (MITF), and sex-determining region Y-box 10 (SOX10), aid in melanoma diagnosis." (PMID 40177537, 2025).
melanoma (continued). "Cytotoxicity tests conducted on melanoma cell lines capable of high tyrosinase overproduction (SK-MEL-3) and low tyrosinase overproduction (Hs294T) indicate that the tested compounds exhibit minimal antiproliferative effects." (PMID 41155937, 2025). "Several melanoma-specific peptides, including gp100, MART-1, MAGE proteins, and tyrosinase, have been widely studied as immunogenic targets in vaccine development." (PMID 40725830, 2025). "LHMW inhibited an α-MSH-induced increase in tyrosinase, TRP1, and DCT expression at both protein and mRNA levels in mouse B16 melanoma cells." (PMID 40672371, 2025). "Pre-treatment of B16 melanoma cells with 0.1 mg/mL PTS for 1 h, followed by exposure to 20 nM α-MSH, significantly inhibited tyrosinase activity." (PMID 40076896, 2025). "The extract inhibited tyrosinase activity (IC50 = 0.713 mg/mL) and reduced melanin production (IC50 = 0.711 mg/mL) in the melanin-producing B16F10 mouse melanoma cell line." (PMID 39203946, 2024). "The effects of AHYYD on tyrosinase activity, melanin production, and antioxidant enzyme activities were investigated in mouse B16F10 melanoma cells." (PMID 39195475, 2024). "Melanin content is reduced by treatment with CC-EO or its major components through the inhibition of tyrosinase activity and its expression in α-MSH-induced B16 melanoma." (PMID 38791435, 2024). "Recent studies investigated the role of antibodies against melanocyte differentiation antigens, including tyrosinase, as predictive markers for immune checkpoint inhibitor [ICI] therapy in melanoma patients." (PMID 39766118, 2024). "Animal experiments also indicated that paeonol significantly reduced tyrosinase activity and melanogen formation in mouse B16F10 melanoma cells, and alleviated UV-induced skin hyperpigmentation symptoms in brown guinea pigs." (PMID 39588155, 2024). "LFP reduced the expression of TYR, tyrosinase-related protein (TRP) 1, and TRP2 in melanoma B16 cells, hence inhibiting the synthesis of melanin." (PMID 39199283, 2024). "The effects of YPNPY on tyrosinase activity, melanogenesis, and antioxidant enzyme activities were investigated in mouse B16F10 melanoma cells." (PMID 39330301, 2024). "Ganodermanondiol demonstrates anti-pigmentation potential by inhibiting tyrosinase activity and melanin biosynthesis in B16F10 melanoma cells." (PMID 38474692, 2024). "AUR has also demonstrated anti-melanogenic activity by directly inhibiting tyrosinase and modulating the expression of major melanogenesis-related genes, including tyrosinase, TRP-1, and dopachrome interconversion isomerase, in mouse melanoma cell lines." (PMID 39204367, 2024). "According to recent studies, MITF is required for melanin synthesis, but MITF is unable to induce the expression of tyrosinase and TYRP1 in B16 mouse melanoma cells or human melanocytes." (PMID 38711645, 2024). "In our analysis of pediatric melanoma samples, we made several key findings regarding the expression of NY-ESO-1, tyrosinase, MAGE-A3, and TPTE." (PMID 38890171, 2024). "From the synthetic series, we selected the most potent tyrosinase inhibitor (compound 13) and activator (compound 14) and evaluated their toxicity to the skin cells by MTT assay in the B16F10 melanoma cells from Mus musculus skin." (PMID 38448547, 2024). "Further, we detected signature melanosomal markers TYR, DCT, GPR143, and GPNMB in the melanosomes derived from melanoma cells, fibroblasts and keratinocytes (Fig. EV2I)." (PMID 38719996, 2024). "Among the limited antigens recognised in canine tumours, tyrosinase was chosen as a target for OMM in dogs, paralleling its use in human and mouse melanomas." (PMID 39728968, 2024). "RES reduced the expression of melanogenesis-related proteins, such as tyrosinase, tyrosinase-related protein 1 (TYRP1), TYRP2, and MITF in melanoma cells." (PMID 39337478, 2024).